IL6 (interleukin 6)
Diseases named in the same sentence as IL6 in open-access papers (continued):
Sharing a sentence is not in itself a finding about the gene and the disease.
cancer (continued). "The clinical consequences of lower circulating concentrations of leptin and the greater concentrations of glucose, cortisol and interleukin-6 in cancer patients in the fed state are likely to be profound." (PMID 15026790, 2004). "Over the feeding period, the area under the curve for glucose, cortisol and interleukin-6 were greater in the cancer group compared with the control group (P<0.05), whereas leptin was significantly less for the cancer group (P<0.05)." (PMID 15026790, 2004). "Cancer patients with elevated C-reactive protein concentrations had greater concentrations of interleukin-6 (P<0.01) and interleukin-1 receptor antagonist (P<0.05)." (PMID 15570310, 2004). "The value of the present study is that it clearly identifies IL-6 from other candidate mediators of the increase in C-reactive protein concentration in a homogenuous cohort of cancer patients." (PMID 15570310, 2004). "In the present study, at baseline, weight-losing cancer patients had less fat, lower leptin concentrations and had increased concentrations of the catabolic mediators cortisol and interleukin-6." (PMID 15026790, 2004). "Such an intervention would allow critical examination of the inter-relationships between circulating concentrations of leptin, interleukin-6 and fat oxidation during feeding in healthy subjects and weight-losing cancer patients." (PMID 15026790, 2004). "High circulating fibrinogen levels are encountered in cancer patients and in this study we confirmed previously found correlations between serum IL-6 and circulating plasma fibrinogen and D-dimers." (PMID 12454774, 2002). "Recently, the serum level of interleukin (IL)-6 has been shown to correlate with disease progression and prognosis of cancer patients." (PMID 10408408, 1999). "We have compared the platelet number and the serum concentration of vascular endothelial growth factor (VEGF), basic fibroblast growth factor (bFGF) and interleukin-6 (IL-6) in 80 blood samples of 50 patients with advanced cancer." (PMID 10360671, 1999). "In pathological sections and ESCC cell lines, message of IL-6 was identified by ISH in cancer cells." (PMID 10408408, 1999). "In addition, they inhibit apoptosis by the SDF-1/CXCR4 axis, and promote cancer stemness by IL-6/STAT3/Notch signalling." (PMID 41476776, 2026). "In NAT samples, older patients with recurrence demonstrated upregulation of inflammatory and cancer-associated pathways-including phagosome formation, IL-17, IL-6, and Th2 signaling-that were absent or downregulated in young patients." (PMID 41836506, 2026). "In PIN and cancer tissue, atypical intraluminal cells and cancer cells can express IL-6." (PMID 41596531, 2026). "Pro-inflammatory cytokines like interleukin-6 (IL-6) and tumor necrosis factor-alpha (TNF-α) have been implicated in cancer progression and may influence CRC outcomes." (PMID 41792766, 2026). "Additionally, TAMs promote allogeneic CD10hi cancer stem cells (CSC) through IL-6/STAT3/CD10 signaling." (PMID 41417432, 2025). "CRP and IL-6 levels have been reported to be correlated in many series and different cancer types." (PMID 39754984, 2025). "The observation that the risk of cancer-related mortality and lung metastasis is higher in SARS-CoV-2-infected patients and the demonstration that IL-6 associated with SARS-CoV2 infection can awaken dormant breast carcinoma cells metastasized in the lung of mice support this possibility." (PMID 41375068, 2025). "Interleukin 6 (IL-6)is a cytokine produced by various cells, including T- and B-lymphocytes, monocytes/macrophages, neutrophils, fibroblasts, endothelial cells, hepatocytes, and mesangial cells, as well as cancer cells." (PMID 40863515, 2025). "IL-6 is known to produce skeletal muscle wasting in cancer cachexia." (PMID 41392310, 2025). "Moreover, IL-6 can promote the process of epithelial-mesenchymal transition (EMT) in cancer cells, enhancing their ability to invade surrounding tissues." (PMID 41346580, 2025).
cancer (continued). "Also, certain markers of inflammation (e.g., CRP, IL-6) are elevated in chronic diseases, such as cancer, and have a relationship with poor mental health." (PMID 40566289, 2025). "Notably, tumor necrosis factor-α (TNF-α) and IL-6 frequently establish a positive feedback loop that drives cancer progression." (PMID 40149421, 2025). "The oncogenic KRAS G13D mutation in MDA-MB-231 may explain the suppression of the IFN-I response and the activation of NF-κB signaling and IL-6 expression, which have been already reported for KRAS-mutated cancers." (PMID 40691137, 2025). "Besides their supporting impact on cancer cell proliferation, survival, and metastatic dissemination, some reports indicate IL-6-mediated activation and proliferation of T lymphocytes." (PMID 39857957, 2025). "Secreted IL-6 could promote the polarization of macrophages into M2-like phenotype which enhancing pro-metastatic effects on cancer cells." (PMID 40909173, 2025). "In addition, IL-6 and miRNA-31 are synergistic in cancer stem cell activity, with higher specificity of salivary IL-6 for OSCC, and improved specificity by the combination of IL-6 mRNA and miRNA-31 as biomarkers." (PMID 39911325, 2025). "Therefore, IL-6 inhibitors are being studied for their potential application as key molecules in cancer therapy that target the IL-6/JAK2/STAT3 signaling pathway." (PMID 40725854, 2025). "The immunological role of IL11 + CAF in cancer is not clear, but highly expressed genes, including IL-6 cytokine family (IL6, IL11, OSM) are associated with immunotherapy resistance." (PMID 39757146, 2025). "Such cell communication may promote secretion of pro-cancer inflammatory cytokines (e.g., IL-6, TGF-β) while inhibiting effector T cell recruitment." (PMID 40630945, 2025). "Researchers demonstrated an association between polymorphisms in the genes encoding IL-1β and IL-6 and cancer-related lack of energy." (PMID 40298695, 2025). "IL-6 is a well-known inflammatory cytokine that not only participates in various inflammatory responses but also plays a crucial role in inflammation-related cancers." (PMID 41051603, 2025). "Later, when IL-6 trans-signaling was proven to be the pathological arm of IL-6, selective inhibitors emerged and have been showing efficacy in multiple clinical and pre-clinical models of inflammation and cancer." (PMID 38980514, 2025). "The authors have shown that the connections between IL-6, CRP, and TNF-α and cancer risk may be site-specific." (PMID 40584290, 2025). "In summary, IL-6 signaling regulates cancer cell proliferation, CSC renewal, and metastasis." (PMID 39896297, 2025). "Immune function may be improved, and inflammation may be reduced through PA; a study conducted in mice found that treadmill running led to lower interleukin-6 (IL-6) levels, a cytokine that plays a role in promoting cancer development." (PMID 41141880, 2025). "Additionally, cancer cell-derived extracellular vesicles contain IL-6, which promotes HSL phosphorylation and increased lipolysis." (PMID 40227577, 2025). "Moreover, Hallmark gene set for cancer‐related pathways (e.g., EMT, IL6 and TNFα signals) were exclusively enriched in ALB+KRT7+ EPCs from AC samples." (PMID 39834100, 2025). "In addition to this, it has an immunomodulatory effect by inhibiting the pro-inflammatory NF-κB pathway and reducing the production of cytokines, such as IL-6, which promote cancer progression." (PMID 40286136, 2025). "The oncogenic effects of AATF may be mediated through its influence on multiple cancer-related signaling pathways, such as the modulation of c-Myc translation, the IL-6/IL-6R signaling axis, and the Src/p190B pathway." (PMID 39911629, 2025). "We previously found that IL-6 signaling promotes the differentiation of MDPs into immunosuppressive macrophages rather than dendritic cells, further explaining their pro-metastatic role in cancer." (PMID 40822347, 2025).
cancer (continued). "Moreover, we previously demonstrated that USP24 stabilizes p300 to increase IL-6 transcriptional activity in the TAMs and accelerate cancer malignancy." (PMID 40238877, 2025). "However, in chronic inflammatory states (such as in the elderly or cancer patients), persistently elevated IL-6 exerts pro-inflammatory and muscle-wasting effects." (PMID 41140691, 2025). "The pathway may be activated by cytokines and growth factors secreted by CAFs, such as COX2 (PTGS2)/PEG2 (PTGER2) or IL6 which were up‐regulated in PM CMS4, or through pathway‐related genetic mutations in the cancer cells, such as KRAS mutations." (PMID 39739693, 2025). "This indicates that IL-6 can participate in cancer-induced bone pain in females." (PMID 40332543, 2025). "IL6 is a central cytokine in the cytokine-cytokine receptor interaction and IL-17 signaling pathways, where it orchestrates immune responses and maintains chronic inflammation, a key factor in both T2D and cancer." (PMID 40127075, 2025). "In response to chronic IL-6-driven inflammatory cues, the liver enhances gluconeogenesis while promoting adipose lipolysis and skeletal muscle proteolysis, metabolic adaptations that collectively culminate in cancer cachexia." (PMID 41256541, 2025). "Similarly, in human ovarian A2780 cancer cells, IL-6 stimulates CD59 expression at low concentrations, but at high concentrations or with IL-8, it presents a post-transcriptional inhibitory effect." (PMID 40370471, 2025). "IL-6, a cytokine that regulates immune functions and promotes tumorigenesis, further mediates this relationship by fostering a pro-inflammatory environment that supports cancer cell growth and survival." (PMID 40485741, 2025). "Additionally, research has revealed that the release of docetaxel-induced protumor cytokines interleukin-6 (IL-6) and granulocyte colony-stimulating factor (G-CSF) stimulate the outgrowth of dormant cancer cells both in vitro and in vivo." (PMID 39934876, 2025). "Using pathway inhibitors and anti-cancer drug Dasatinib, this change was shown to be driven by interleukin 6 (IL-6)–STAT3 signaling, which could be partially reversed." (PMID 40966450, 2025). "IL‐6 expression by Mφs can influence both cancer cells and CAFs." (PMID 40056038, 2025). "Furthermore, a broader role for IL‐6 in promoting cachexia in cancer is suggested by a recent systematic review of gene polymorphisms associated with cancer cachexia." (PMID 39764565, 2025). "However, further investigations are needed to dissect a possible connection between Fusobacterium load and IL6-mediated cancer progression." (PMID 40895532, 2025). "TGF-β, produced by cancer cells, increases IL-6 expression in CAFs, which in turn influences EMT." (PMID 40136652, 2025). "Siltuximab, an anti-IL-6 antibody, has demonstrated significant therapeutic benefits in the management of diverse human cancers, whether administered as a monotherapy or in combination with other chemotherapy agents." (PMID 41291543, 2025). "According to the coculture model, THC treatment may also harm the development and colony formation of cancer cells and the MDSCs' production of IL‐6." (PMID 41179371, 2025). "Previous reports highlighted stimulation of interleukin‐6 (IL‐6), interleukin‐8 (IL‐8), and growth‐regulated alpha protein (CXCL1) production by keratinocyte‐conditioned medium in fibroblast cells and implicated these cytokines in cancer." (PMID 40621923, 2025). "The transition from inflammation to cancer may be mediated by several regulatory molecules, including chemokines, proinflammatory cytokines, TNF, and IL-6, which are crucial in promoting the growth, proliferation, and invasion of cancer cells." (PMID 40051564, 2025). "Increased ghrelin sensitivity, decreased leptin concentrations, elevated levels of IL-6 and blood glucose, and hyperactivity of HO neurons (increased cFos immunoreactivity) were observed in cancer mouse models during the development of sleep debris in the late phase of tumor growth." (PMID 40740866, 2025).
cancer (continued). "The ‘browning’ conversion in visceral adipose tissue (VAT) may be supported by cancer cells and by the oncoinflammatory niche, which is characterized by high level of pro-inflammatory cytokines, such as interleukin 6 (IL-6) or tumor necrosis factor α (TNF-α)." (PMID 40227577, 2025). "However, the role of circRNAs has been studied only in the context of IL‐6 and IL‐10 signaling in cancer." (PMID 40356340, 2025). "Moreover, IL-6 facilitates the metastatic spread of invasive cancer cells by inducing transcriptional activators of epithelial-mesenchymal transition." (PMID 40160826, 2025). "Furthermore, IL-6 levels are elevated in various cancers, and the amount of circulating IL-6 correlates with the prognosis in patients with cancer." (PMID 40564167, 2025). "In addition, the role of IL-6 and the complexity of the use of IL-6 blockade in cancer therapy should be noted." (PMID 40255422, 2025). "Similarly, IL-6 directly promotes cancer cell proliferation by activating signal transducer and activator of transcription 3 (STAT3), which drives cell cycle progression." (PMID 40648921, 2025). "Interleukin‐6 (IL‐6) links inflammation to cancer and acts as a key information‐transmission hub." (PMID 40095296, 2025). "Adipocytes readily secrete pro-inflammatory adipokines, such as tumor necrosis factor-α (TNF-α), monocyte chemoattractant protein-1 (MCP-1), and interleukin-6 (IL-6), which recruit immune cells and amplify inflammatory processes, thereby promoting cancer development, progression, and metastasis." (PMID 40823082, 2025). "The resultant increased secretion of IL-6 could in turn lead to autocrine activation of downstream signalling pathways and impact on cancer cell migration and invasion." (PMID 40371393, 2025). "Elevated IL6 levels also emerge in the aging population, especially in post-menopausal women, where it contributes to immune dysfunction and a favorable environment for cancer development." (PMID 40427188, 2025). "In cancer therapy, their combination with PD‐L1 blockade has shown therapeutic efficacy in mouse models of melanoma and pancreatic cancer by disrupting the immunomodulatory interactions mediated by IL‐6." (PMID 40656546, 2025). "The IL‐6/JAK/STAT3 activation also enhances metastasis ability of cancer cells via induction of EMT in gastrointestinal cancers by the upregulation of EMT‐inducing transcription factors such as EMT‐transcriptional factors, such as SNAIL, ZEB1, JUNB, and TWIST‐1." (PMID 41346572, 2025). "Interestingly, SW1116 cancer cells also showed increased IL-6 secretion following treatment with betulin relative to EB5 and 5-FU (p < 0.01 and p < 0.05, respectively)." (PMID 41256010, 2025). "While our cytokine array results demonstrate that EMD-CM from cancer cells primarily induces M2 polarization in macrophages, we also observed an increase in cytokines traditionally associated with M1 polarization, such as TNF-α, IL-1β, and IL-6." (PMID 39941817, 2025). "However, in many cancers, the aberrant form of glycosylated IL-6 reduces STAT3 activation, leading to increased activity of the SRC-YAP-SOX2 signaling axis." (PMID 41376623, 2025). "Moreover, recent research has shown that IL-6 secreted by adipocytes drives STAT3 signaling to induce HIF1α in cancer cells, with HIF1α known to regulate ANGPTL4 expression." (PMID 40616161, 2025). "IL-6 is a proinflammatory cytokine that plays a complex role in cancer progression." (PMID 39762212, 2025). "First, although we observed that MBIs increase the circulatory IL-6 levels in cancer, whether they exert inhibitory effects on tumors or prevent their recurrence warrants further cohort studies." (PMID 40281902, 2025). "Additionally, CAF-derived IL-6 activates the JAK2/STAT3 pathway in cancer cells, inducing EMT and enhancing metastatic potential, thereby reinforcing a positive feedback loop that sustains IL-6 expression." (PMID 40718440, 2025).
cancer (continued). "The positive association between cancer and IL-10 was mediated 5.6% by TNFR1 and 4.1% by IL-6 independently, while the positive association for GDF15 was mediated 36.1% by TNFR1 and 10.5% by IL-6 independently." (PMID 41280118, 2025). "Emerging evidence implicates interleukin 6 (IL-6) as a critical mediator of chemoresistance through cancer stem cell (CSC) enrichment and metastasis promotion via epithelial–mesenchymal transition (EMT) induction, ultimately contributing to cisplatin therapy failure." (PMID 40733153, 2025). "By inhibiting NF-kB activation, SsnB may diminish the expression of its target cytokines, including TNF-α, IL-1β, and IL-6, which are critical for maintaining cancer cell viability and immune evasion." (PMID 40143078, 2025). "Once the stress in the host is over, the synthesis of IL-6 ends, so uncontrolled, excessive, or persistent IL-6 production is related to a pathological role in the development of various inflammatory diseases and cancers." (PMID 40422059, 2025). "Furthermore, the KRAS signaling pathway, IL6/JAK/STAT3 pathway, and IL-2/STAT5 pathway were strongly linked to STX7 expression in cancer." (PMID 40999361, 2025). "IL-6 plays an important role in cancer-related inflammation and cancer progression processes." (PMID 41614883, 2025). "Interestingly, six genes among these (ABCB1, FGF2, CXCR4, IL6, PSMB9, and CLU), as well as UGCG, are known to be highly associated with cancer resistance to platinum-based chemotherapy." (PMID 40507922, 2025). "13-HpOTrE (r) diminished the release of interleukin-6 and decreased the viability of cancer cells." (PMID 40606159, 2025). "It has been shown that the use of TGF-β and IL-6 inhibitors sensitizes cancer cells to cisplatin." (PMID 40136652, 2025). "We therefore propose that IL-6’s normally adaptive substrate-mobilizing role becomes maladaptive in cancer: excess FAs that cannot be eniciently oxidized are progressively redirected into membrane lipids and bioactive sphingolipids, predisposing to lipid-driven organelle dysfunction." (PMID 41256541, 2025). "At the clinical level, previous meta-analyses have provided preliminary evidence that exercise can improve common metabolic disturbances in cancer patients, including blood glucose, insulin, and triglycerides, as well as inflammatory markers such as IL-6, C-reactive protein (CRP), and TNF-α." (PMID 40895542, 2025). "Other cytokines such as IL-6 in cancer could be a potent growth factor for many types of cancer cells." (PMID 40563999, 2025). "In the TME, IL-6 is secreted by Fb, as well as cancer cells, immune cells, and endothelial cells." (PMID 39858048, 2025). "Conversely, other authors have suggested that low plasma levels of IL-6 may correlate with the occurrence of irAEs, as IL-6 is known to play a role in promoting immune evasion by cancer cells." (PMID 41019062, 2025). "Consequently, IL6-mediated immune dysregulation represents a critical barrier to effective cancer immunotherapy and serves as a target for therapeutic interventions aimed to restore immune function." (PMID 40427188, 2025). "We also acknowledge that IL-6 levels in these models differ from those observed in human cancers, which could limit the direct applicability of our findings to clinical practice." (PMID 40275022, 2025). "In addition, in the between group analyses, there were significant changes in favour of HIIT when measuring IL-6 levels and the inhibitory effects on cancer cells immediately post exercise." (PMID 40608178, 2025). "While our study also revealed novel findings, such as a possible activation of the IL6-STAT-IDO pathway feedback loop or the cellular responses to hypoxia in cancer cell lines, these findings require further validation using orthogonal technologies, such as WB, IHC or ELISA." (PMID 40348885, 2025).